CTNNB1 (catenin beta 1)
Diseases named in the same sentence as CTNNB1 in open-access papers (continued):
Sharing a sentence is not in itself a finding about the gene and the disease.
hepatocellular carcinoma (continued). "Gain-of-function mutations in the CTNNB1 gene are found in around 30% of cases of hepatocellular carcinoma (HCC)." (PMID 36612190, 2022). "Studies suggest that mutations in the CTNNB1 gene are predictive of response to immunotherapy, an emerging therapy for advanced hepatocellular carcinoma (HCC)." (PMID 33827453, 2021). "Activating mutations of CTNNB1, the gene encoding β-catenin, are present in 20–40% of hepatocellular carcinomas (HCC), the most frequent primary liver cancer, and are the most common oncogenic driver in HCC." (PMID 26974334, 2016). "However, mutations in CTNNB1 are highly prevalent in hepatocellular carcinoma (24%), sarcoma (44%) and testicular cancer(24%), suggesting that these cancers may potentially have increased sensitivity to RK-33." (PMID 26311743, 2015). "In hepatocellular carcinoma (HCC), AXIN1 mutations associate with a poor-prognosis subtype distinct from β-catenin-mutant HCC (CTNNB1)." (PMID 41550750, 2026). "CTNNB1 gene mutations, responsible for encoding β-catenin, are intricately linked with a spectrum of malignancies, encompassing hepatocellular carcinoma (HCC), pancreatic cancer, colorectal cancer (CRC), gastroesophageal junction carcinoma, and gastric adenocarcinoma." (PMID 39123414, 2024). "Strikingly, in hepatocellular cancer, TACSTD2-high tumors had a much lower prevalence of CTNNB1 mutations (25.0% vs 55.5%)." (PMID 38986529, 2024). "In CTNNB1-mutant hepatocellular carcinoma, β-catenin escapes degradation by the ubiquitin-proteasome system and accumulates in the nucleus to form a complex with TCF/LEF." (PMID 37046727, 2023). "A previous study using a human CTNNB1-mutated HCC dataset and an in vivo hepatocellular carcinoma model showed that the upregulation of the Wnt/β-catenin pathway significantly increases fatty acid oxidation." (PMID 37109525, 2023). "The CTNNB1 3’UTR splice variant was shown to promote cell proliferation and migration in hepatocellular carcinoma (HCC) and colon adenocarcinoma (COAD)." (PMID 36834627, 2023). "CTNNB1 is altered in 3.10% of all cancers, with lung, colon, prostate, and hepatocellular carcinomas having the highest rate of prevalence." (PMID 36982429, 2023). "Compared to adult hepatocellular carcinoma (HCC), HBL is characterized by a low rate of genetic mutations that are mainly observed in CTNNB1 (β-catenin) and NRF2 genes." (PMID 36551548, 2022). "It has been well described that green hepatoma, characterized by tumor cholestasis and showing a high-intensity nodule on Gd-EOB-DTPA-enhanced-MRI, generally shows a good prognosis and carries CTNNB1 mutations." (PMID 35053606, 2022). "We found that the expression of CCL19 in CTNNB1 wild-type hepatocellular carcinoma cells (HepG2 cells) is higher than that in CTNNB1 mutant cells (Huh6 and SNU398 cells)." (PMID 36189258, 2022). "By translating a novel 370-aa β-catenin isoform, a circRNA derived from CTNNB1 pre-mRNA promotes the proliferation hepatocellular carcinoma cell with the mechanism of activating the Wnt signaling pathway." (PMID 34153004, 2021).
hepatocellular carcinoma (continued). "For example, DANCR was verified to interact with 3′UTR of CTNNB1 mRNA in hepatocellular carcinoma, thus competitively blocking miRNA site and reversing miRNA-mediated CTNNB1 suppression." (PMID 34722539, 2021). "Beta-catenin pathway activation or an increased CTNNB1 score resulted in T cell exclusion and demonstrated resistance to ICIs in melanomas and hepatocellular carcinomas (HCCs)." (PMID 32414098, 2020). "For instance, lncRNA DANCR induced CTNNB1 to enhance the stemness of hepatocellular cancer cells and drive tumorigenesis." (PMID 32239639, 2020). "CTNNB1 is considered the cancer drivers for hepatocellular carcinoma development with variable frequencies depending on the etiology." (PMID 30134863, 2018). "For example, DANCR can interact with the binding site of miR-199a/320a/214 in 3’UTR of CTNNB1 to inhibit the suppression of CTNNB1 by miRNAs, thus promoting stemness features of hepatocellular carcinoma." (PMID 30419948, 2018). "Yuan SX suggested that DANCR increased stemness features of hepatocellular carcinoma by derepression of catenin beta 1 (CTNNB1)." (PMID 29753317, 2018). "A Gnmt knockout mouse model of hepatocellular carcinoma has shown that genes related to the Wnt pathway (e.g., Ctnnb1, Ccnd1, and Myc) were up-regulated, indicating that GNMT is a tumor suppressor gene for liver cancer." (PMID 27469031, 2016). "Of 109 patients with hepatocellular carcinoma, 41 (39.0%) and 15 (14.6%) harbored TERT and CTNNB1 mutations, respectively." (PMID 27661004, 2016). "It would be especially interesting, for example, to study wild-type CTNNB1 hepatoma cells which express β-catenin and metabolic enzymes at levels even closer to the in vivo situation." (PMID 22296956, 2012). "In contrast to other hepatic tumors, FNH does not commonly express beta-catenin (CTNNB1) or HNF1α mutations, which are seen in hepatocellular carcinomas and adenomas, respectively." (PMID 40448211, 2025). "In hepatocellular carcinoma (HCC), activating mutations in β-catenin (CTNNB1) occurs by 30–44 %." (PMID 39253139, 2024). "Comprehensive analysis of clinical samples has recently identified molecular and immunological classification of hepatocellular carcinoma (HCC), and the CTNNB1 (β-catenin)-mutated subtype exhibits distinctive characteristics of immunosuppressive tumor microenvironment." (PMID 34429454, 2021). "Interestingly, a recent study found that the β-catenin gene CTNNB1 is a direct target of miR-214 in human hepatocellular carcinoma." (PMID 28076844, 2017). "TERT promoter and CTNNB1 mutations were only observed in hepatocellular carcinomas but not in precursor lesions." (PMID 27661004, 2016).
hepatocellular carcinoma (continued). "Genetic alterations of TERT and CTNNB1 have been documented in hepatocellular carcinoma." (PMID 27661004, 2016). "Recurrent somatic mutations in the promoter region of telomerase reverse transcriptase (TERT) gene and in the exon 3 of CTNNB1 gene have been recognized as common events in hepatocellular carcinoma (HCC) with variable frequencies depending on etiology and geographical region." (PMID 27276713, 2016). "Furthermore, knockdown of CTNNB1 in two mouse hepatoma cell lines, as well as in vivo knockout of CTNNB1 in mouse hepatocytes, both resulted in a significantly weaker upregulation of Cyp1a1 transcription after activation of AHR." (PMID 25286307, 2014). "Mutations or overexpression of the beta catenin gene (CTNNB1), a key member of the Wnt signaling pathway, have been found in all other categories of hepatocellular neoplasms including hepatoblastomas, hepatic adenomas, and typical hepatocellular carcinoma." (PMID 24278737, 2012). "However, this oncogenic monopoly is not universal; CTNNB1 mutations often replace APC loss in hepatocellular carcinoma (HCC) and medulloblastoma, highlighting the context-dependent nature of WNT perturbation." (PMID 40874062, 2025). "However, analyses of TERT promoter and CTNNB1 mutations in hepatocellular carcinoma tumor samples have not been performed in the Korean population, where hepatitis B virus-related hepatocellular carcinoma is prevalent." (PMID 27661004, 2016). "In a mouse hepatoma cell line, TCDD activated expression of an AHR reporter gene (luciferase driven by a promoter containing three DREs) to a significantly greater extent in cells expressing a stabilized CTNNB1 (CTNNB1S33Y mutation) than in control cells expressing wild type CTNNB1." (PMID 25286307, 2014).
hepatocellular carcinoma (continued). "Hepatocellular carcinoma (HCC) is a fatal disease characterized by early genetic alterations in telomerase reverse transcriptase promoter (TERTp) and β-catenin (CTNNB1) genes and immune cell activation in the tumor microenvironment." (PMID 35962322, 2022). "Wnt presentation in tissues with hepatocellular carcinoma are reported in two classes named CTNNB1 and Wnt-TGF-B with different characteristics in liver carcinoma." (PMID 33585001, 2020). "Also, in hepatocellular carcinoma (HCC), METTL3 stabilizes LINC00958, Snail, and CTNNB1, thereby contributing to cellular processes such as lipogenesis, proliferation, metastasis, and tumor growth." (PMID 38966069, 2024). "Specifically, exposure to TCDD did not affect mRNA levels of CTNNB1 target genes Axin2 and Lgr5 in the hepatoma cell line, nor did 3-methylcholanthrene (3MC, an AHR agonist) affect mRNA levels of the same two target genes in the liver." (PMID 25286307, 2014). "We note that our dataset did not have any CTNNB1-mutant hepatocellular carcinoma cell lines." (PMID 34313788, 2021). "Recently, two well-differentiated and non-proliferative subclasses of hepatocellular carcinoma (HCC), known as periportal-type (wild-type CTNNB1) and perivenous-type (mutant CTNNB1), have been identified." (PMID 29899848, 2018).
breast carcinoma (129 papers, 2008 to 2025). "In the absence of any apparent genetic mutations, what then is the cause of elevated CTNNB1 levels in human breast cancer?" (PMID 32083079, 2020). "Perhaps, over expression of TCF-4 and CTNNB1 genes were associated with the activation of MAPK gene in breast cancer cell lines with different degrees of invasiveness." (PMID 30379886, 2018). "In summary, this study indicated that the genetic polymorphisms of CDH1 and CTNNB1 were associated with breast cancer susceptibility and prognosis." (PMID 26285011, 2015). "Genotype and allele frequencies of the selected SNPs in CDH1 and CTNNB1 and their associations with risk of breast cancer." (PMID 26285011, 2015). "This study indicated that the genetic polymorphisms of CDH1 and CTNNB1 were associated with breast cancer susceptibility and patients’ prognosis." (PMID 26285011, 2015). "In regard to increased Ctnnb1 expression, the Wnt/β catenin pathway is involved in normal mammary gland proliferation and development, and associated with poor prognosis in breast cancer." (PMID 24156623, 2013). "In contrast to colorectal cancer (CRC), however, mutation of APC, AXIN or CTNNB1 (β-catenin) is rare in breast cancer, indicating that other mechanisms are responsible for the activation of β-catenin." (PMID 18283316, 2008). "The identification of a mutation in CTNNB1 may lead to the development of new treatments for breast cancer patients." (PMID 35453754, 2022). "Mutation of CTNNB1, which encodes β-Catenin, is rare in breast cancer." (PMID 33234169, 2020). "Moreover, it is known that the Wnt/β-catenin (Ctnnb1) pathway plays an important role in human breast cancers with high activation rates and association with a poor prognosis." (PMID 32793490, 2020). "The activation of the CTNNB1 pathway has been previously linked to breast cancer progression, and thus our data corroborates the importance of this network and suggests an additional therapeutic opportunity to intervene in metastasis establishment and progression." (PMID 32463822, 2020). "Specifically, Wnt signaling activation in metaplastic breast cancers is caused mainly by genetic changes, such as CTNNB1 and APC mutations, whereas Wnt signaling activation in BLBCs and TNBCs is associated mainly with the strong expression of nuclear β-Catenin." (PMID 33234169, 2020). "Beta-catenin encoded by CTNNB1 is a constituent of adherens junctions and acts as an intracellular signal transducer in the Wnt signaling pathway, a pathway that is closely related with the occurrence, development, invasion and metastasis of breast cancer." (PMID 30181805, 2018). "Finally, the use of OncoScantm has allowed us to detected mutations in five genes that have not been shown to be mutated in TCGA subset of Her-2 overexpressing breast cancer: CTNNB1, HRAS, KRAS, NF2 and SMARCB1." (PMID 28247034, 2017). "This study aims to investigate whether the germline variants in CDH1 and CTNNB1 would affect breast cancer susceptibility and patients’ prognosis among Chinese Han women using a haplotype-based association analysis." (PMID 26285011, 2015). "In regard to increased Ctnnb1 (β-catenin) expression, the Wnt/β-catenin pathway is involved in normal mammary gland proliferation and development and is associated with poor prognosis in breast cancer." (PMID 26526858, 2015). "There is also evidence that TCF4 may have a role in breast cancer progression due to its interaction with the β-catenin protein (encoded by the CTNNB1 gene) and the Wnt signaling pathway." (PMID 26043920, 2015).